Y_RNA (Y RNA )
Gene: Miscellaneous RNA gene on chromosome 6 (128,584,390 to 128,584,491, forward strand). Ensembl gene ENSG00000206982.
Homologues: Orthologues: chimpanzee Y_RNA (99% identical), dog Y_RNA (79% identical). Paralogues in human: RNY3 (87% identical), Y_RNA (87% identical), Y_RNA (86% identical), RNY3P1 (85% identical), Y_RNA (85% identical), Y_RNA (84% identical), Y_RNA (83% identical), RNY3P13 (82% identical), RNY3P14 (82% identical), Y_RNA (82% identical), RNY3P11 (81% identical), RNY3P16 (81% identical), and 95 more.